PIAS3 (protein inhibitor of activated STAT 3)
Diseases named in the same sentence as PIAS3 in open-access papers (continued):
Sharing a sentence is not in itself a finding about the gene and the disease.
cancer (28 papers, 2012 to 2025). A tumor composed of atypical neoplastic, often pleomorphic cells that invade other tissues. "The SUMO pathway is also implicated in regulation of stem-like cell properties of cancer cells e.g., via PIAS3 and STAT3." (PMID 34503213, 2021). "Moreover, the Ring-induced reduction of PIAS3 suggests an additional underlying mechanism mediating PIAS3 loss in cancers." (PMID 29950561, 2018). "In addition, PIAS3 plays a risk factor in six cancers, ACC, KIRC, KIRP, LIHC, SARA, and MESO." (PMID 33123273, 2020). "Various lines of evidence suggest that low expression of PIAS3 supports cancer cells proliferation or promotes tumorigenesis." (PMID 38590645, 2024). "Considering these facts, few efforts have been done for the identification of natural activators to restore PIAS3 levels in cancer cells." (PMID 38590645, 2024). "PIAS3 expression was significantly decreased in two cancer types and significantly up-regulated in fifteen cancer types." (PMID 38528630, 2024). "These SUMOylation regulators have lower overall average mutation frequencies in 33 types of cancer, although SENP1, SENP5, SENP7, and PIAS3 regulators have higher mutation frequencies." (PMID 33123273, 2020). "Till now, several studies mentioned that SUMO E1, E2, and E3 enzymes such as Ubc9 and PIAS3 are upregulated in many cancer types." (PMID 30612578, 2019). "On the other hand, differential PIAS3 expression has been observed in a variety of human cancers, including lung, breast, prostate, colorectal, and brain." (PMID 31835700, 2019). "Genomic studies have revealed that MM is characterized by frequent mutations in tumor suppressor genes, making the study of PIAS3 in this cancer highly relevant." (PMID 30259640, 2018). "The first eight of the nineteen targets, PIAS3, p27, RAB10, DBF4, DUSP14, RBPMS, PDPN and CLTC, were considered to be closely associated with cancer progression after a literature review." (PMID 28120918, 2017). "While PIAS proteins can be overexpressed in some cancers, PIAS3 expression is repressed in anaplastic lymphoma, glioblastoma, mesothelioma, and NSCLC, which correlates to constitutive STAT3 activation." (PMID 27148255, 2016). "Growing evidence has revealed that ectopic PIAS3 overexpression can inhibit cell proliferation and induction of apoptosis in cancer cells under certain conditions." (PMID 26768588, 2016). "To date, only a small number of reports focused on PIAS3 participation in cancers involving lung tumors, has been published." (PMID 25137041, 2014). "We identified the SUMO family member PIAS3 as a putative cancer driver gene that is amplified in TCGA datasets." (PMID 24874471, 2014). "Furthermore, increased PIAS3 expression induces apoptosis in cancer cells, highlighting its potential role in cancer suppression." (PMID 40166646, 2025). "Brassinin prevents STAT3 signaling by modulating PIAS3, leading to reduced cancer growth (b)." (PMID 38590645, 2024). "Previous studies have reported that TRIM8 negatively regulates PIAS3 in cancer cell lines." (PMID 28100038, 2017). "We hypothesize that the difference of PIAS3-mediated effects on cell growth between the two types of cancer cell lines is due to the presence of ER." (PMID 26768588, 2016). "Aberrations in a specific STAT3 regulator such as the protein inhibitor of activated STAT3 (PIAS3) may also contribute to cancer development." (PMID 26768588, 2016). "Alterations in specific negative regulators, such as protein inhibitor of activated STAT3 (PIAS3), may contribute to cancer development." (PMID 26768588, 2016). "Little is established, however, about the mechanism of PIAS3 downregulation in cancer." (PMID 25573684, 2015). "PIAS3 plays a significant role in promoting IR resistance, therefore, PIAS3 may be a potentially promising therapeutic approach for cancer treatment." (PMID 24137461, 2013).
cancer (continued). "Recently, tri‐partite motif‐containing protein 8 (TRIM8) has been shown to interact with PIAS3, either by causing its degradation through the ubiquitin‐proteasome pathway or through its exclusion from the nucleus, resulting in enhanced STAT3‐dependent signaling in a subset of cancer cell lines." (PMID 28100038, 2017). "It has been shown that loss of PIAS3 contributes to STAT3 activation and subsequent cell proliferation in many types of cancer, such as malignant mesothelioma, lung carcinoma, and GBM, suggesting that the PIAS3‐STAT3 pathway might also be a signaling pathway that regulates GSC stemness." (PMID 28100038, 2017). "Another natural compound, Curcumin, enhances PIAS3 expressions and inhibits STAT3 phosphorylation in ovarian and endometrial cells in cancer." (PMID 38590645, 2024). "The downregulation of PIAS3 leads to the upregulation of STAT3, which promotes multiple oncogenic pathways; thus, it is an important target for cancer therapies." (PMID 38590645, 2024). "In this study, we analyzed the expression of PIAS family genes (PIAS1, PIAS2, PIAS3, and PIAS4) in 33 different types of cancer." (PMID 38528630, 2024). "In a nutshell, curcumin inhibits JAK-STAT signaling through activation of PIAS3, thus decreasing STAT3 phosphorylation and cancer cell growth." (PMID 38590645, 2024). "On the other hand, inhibition of negative regulators such as PIAS3, SOCS1 and 3 and several cellular phosphatases (SHP1 and 2, PTPRD, PTPRT, PTPN1 and 2, DUSP22) can also lead to STAT3 activation in cancer." (PMID 35145111, 2022). "PIAS3 can activate the GnRH signaling pathway, MAPK signaling pathway, melanogenesis, NOTCH signaling pathway, and biological cancer pathways." (PMID 33123273, 2020). "Studies have also indicated that restoring or overexpressing PIAS3, via repression of STAT3‐mediated oncogenic pathways, shows inhibitory effects on cancer cells." (PMID 30259640, 2018). "Although the Ring construct exhibits its protection on PIAS3 only with excessive nuclear-Smad6 expression, it triggers a reduction of endogenous PIAS3 in native GBM cells and thus demonstrates a cancer-promoting function." (PMID 29950561, 2018). "By directly interacting with phosphorylated STAT3, PIAS3 can block the downstream transcriptional activity of STAT3, which is hyper‐activated in various cancers." (PMID 30259640, 2018). "For example, miR-18a impairs cancer cell growth via inhibition of the expression of CDC42 gene, or negatively regulates the expression of PIAS3, an inhibitor of STAT3." (PMID 28718798, 2017). "The most frequently reported PIAS family member in cancer development are PIAS1 and PIAS3." (PMID 38590645, 2024). "Most frequently reported PIAS family members in cancer development are PIAS1 and PIAS3." (PMID 38590645, 2024). "Considering the effect of PIAS3 on STAT3, the downregulation of PIAS3 expression may play a critical role in augmenting STAT3 signaling in kidney diseases and cancer development." (PMID 39335615, 2024). "Our findings also highlight a role for PIAS3 in EMT and cancer invasion and metastasis." (PMID 28423498, 2017). "However, mechanisms regulating PIAS3 downregulation in human cancers have not been comprehensively studied." (PMID 29950561, 2018).
infection (6 papers, 2010 to 2023). The state of being infected such as from the introduction of a foreign agent such as serum, vaccine, antigenic substance or organism. "We detected differences in the expression levels of IL-6 and PIAS3 during C. burnetii-infection between bovine and human macrophages." (PMID 36793725, 2023). "In contrast, the IL-6 expression level was increased in human macrophages under hypoxia at 24 and 96 h post-infection and the PIAS3 expression level was increased at 24 h post-infection under normoxia." (PMID 36793725, 2023). "This SUMOylation-promoting activity of PIAS3 can be inactivated by the C334S mutation of SP-RING domain, or by siPIAS3 interference during infection." (PMID 34747321, 2021). "The upregulation of PIAS3 and SOCS1 and the significant degradation of unSTAT3 at the later stage of infection may partially explain the reduced expression of STAT3 target genes in the late stage of EV71 infection." (PMID 31575039, 2019). "PIAS3 and SOCS1, two regulators that had been reported to restrict the expression of STAT3 target genes, showed a significant increase of the expression upon infection." (PMID 31575039, 2019).
adenocarcinoma (1 paper, 2015). A common cancer characterized by the presence of malignant glandular cells. "Again, prominent PIAS3 protein expression was observed in A549 adenocarcinoma cells and was greater than that observed in the normal NL-20 cells." (PMID 25573684, 2015). "Furthermore, SCC demonstrates lower expression levels of PIAS3 compared to adenocarcinoma and normal epithelium, in vitro and in vivo, by immunohistochemistry and western blotting, consistent with our previous published data." (PMID 25573684, 2015).
inflammation (1 paper, 2023). Aberrant reaction of the microcirculation characterized by movement of fluid and leukocytes from the blood into extravascular tissues. "Another factor that negatively regulates Th17 cell differentiation and thereby exerts inhibitory effects on the progression of gut inflammation is PIAS3." (PMID 37049797, 2023).
PIAS3 also shares sentences with these, for which no sentence is quoted: adenocarcinoma of the lung (2 papers); chronic lymphocytic leukemia (2); osteosarcoma (2); autoimmune (1); autoimmune glomerulonephritis (1); bladder cancers (1); brain cancer (1); brain infarction (1); brain tumors (1); cervical adenocarcinoma (1); Cognitive impairment (1); Crohn disease (1); graft versus host disease (1); hyperlipidemia (1); ileitis (1); ischemic stroke (1); keratitis (1); kidney diseases (1); liver cancer (1); mesothelioma (1); papillary thyroid cancer (1); retinitis pigmentosa (1); systemic lupus erythematosus (1); Thrombocytopenia (1).